PSG2 (pregnancy specific beta-1-glycoprotein 2)
Synonyms: PSBG2; PSGGB; PSG1; CEA
Tractability: Antibody: UniProt places it where antibodies can reach, with high confidence; UniProt predicts a signal peptide or a membrane-spanning region; its Gene Ontology location is reachable by antibodies, with medium confidence.
Gene: Protein-coding gene on chromosome 19 (43,064,209 to 43,083,045, reverse strand). Ensembl gene ENSG00000242221.
Subcellular location: Secreted
Pathways (Reactome):
Hemostasis: Cell surface interactions at the vascular wall
Gene Ontology:
Biological process: cell migration; female pregnancy; heterophilic cell-cell adhesion; homophilic cell-cell adhesion
Cellular component: plasma membrane; extracellular region
Genetic constraint (gnomAD): Loss-of-function variants: 49 observed, 36.33 expected, observed/expected ratio (o/e) 1.35, 90% interval 1.07 to 1.71. The synonymous counts are far from expectation, so gnomAD's model fits this gene poorly and the ratio says little. Missense variants: 605 observed, 411.87 expected, observed/expected ratio (o/e) 1.47, 90% interval 1.37 to 1.57. Synonymous variants: 261 observed, 155.59 expected, observed/expected ratio (o/e) 1.68, 90% interval 1.51 to 1.86.
Homologues: Orthologues: chimpanzee PSG2 (92% identical). Paralogues in human: PSG11 (90% identical), PSG7 (84% identical), PSG8 (84% identical), PSG3 (84% identical), PSG1 (84% identical), PSG4 (83% identical), PSG6 (83% identical), PSG9 (79% identical), PSG5 (60% identical), CEACAM1 (46% identical), CEACAM5 (44% identical), CEACAM8 (42% identical), and 12 more.
Diseases named in the same sentence as PSG2 in open-access papers:
PSG2 is named in the same sentence as 9 diseases in open-access papers, as found by Europe PMC text mining. Sharing a sentence is not in itself a finding about the gene and the disease. The quoted sentences say what the papers report.
cervical cancer (3 papers, 2018 to 2024). A primary or metastatic malignant neoplasm involving the cervix. "In cervical cancer, the PSG2 locus harbors copy number gain associated with increased expression in cancer compared to normal from bulk tissue biopsies." (PMID 39193365, 2024).
colorectal cancer (1 paper, 2005). A primary or metastatic malignant neoplasm that affects the colon or rectum. "PSG2 was expressed at very low levels in both tumour and normal mucosa from colorectal cancer cases." (PMID 15982419, 2005).
dementia (1 paper, 2022). Loss of intellectual abilities interfering with an individual's social and occupational functions. "Several case-control studies have shown that low levels of PSG2 are associated with pre-eclampsia, which, in turn, has been suggested to be associated with an increased risk of dementia later in life." (PMID 35788729, 2022).
trisomy 16 (1 paper, 2024). "In this work, it was shown that in the studied group of spontaneousabortions with trisomy 16, the level of methylationof the PRDM1 and PSG2 genes was significantly increasedcompared with induced abortions." (PMID 38680176, 2024).
tumor (3 papers, 2005 to 2025). "Molecular markers: Alongside established TEP biomarkers (ITGA2B, IGFBP2), PSG2 indicates tumor-derived RNA uptake." (PMID 41226816, 2025). "The PSG3 gene had the highest expression level in both male and female tumor samples whereas PSG2, PSG7, and PSG11 had relatively lower expression levels." (PMID 40257008, 2025). "To examine whether PSG9 expression was specific for tumours, we examined expression of PSG2 in the same tumours which had exhibited deregulated PSG9 expression." (PMID 15982419, 2005).
cancer (2 papers, 2024). A tumor composed of atypical neoplastic, often pleomorphic cells that invade other tissues. "In the second family in which MPT21 and two relatives were tested, we found four LP variants (BPIF1, BCORL1, ROPN1, and PRSS3) and four other cancer-related genes (TUBB2B, CFAP54, PSG2, and SIRPB1)." (PMID 39408606, 2024). "Variants in four genes (ROPN1, PRSS3, BPIFB1, and BCORL1) were detected in all individuals from Family 2, while four (TUBB2B, CAFAP54, PSG2, and SIRPB1) were exclusive of the MPT21 index case and her relative with cancer (MPT21.2)." (PMID 39408606, 2024).
PSG2 also shares sentences with these, for which no sentence is quoted: asthma (1 paper); autism (1); gestational hypertension (1).